SNORD116-23 (small nucleolar RNA, C/D box 116-23)
Synonyms: HBII-85-23
Gene: Small nucleolar RNA gene on chromosome 15 (25,091,786 to 25,091,877, forward strand). Ensembl gene ENSG00000207375.
Gene Ontology:
Biological process: RNA processing
Cellular component: nucleolus
Homologues: Orthologues: chimpanzee SNORD116 (100% identical), macaque SNORD116 (99% identical), guinea pig SNORD116 (88% identical), guinea pig SNORD116 (84% identical). Paralogues in human: SNORD116-15 (95% identical), SNORD116-16 (95% identical), SNORD116-17 (93% identical), SNORD116-19 (93% identical), SNORD116-14 (92% identical), SNORD116-18 (92% identical), SNORD116-20 (92% identical), SNORD116-21 (92% identical), SNORD116-22 (92% identical), SNORD116-24 (92% identical), SNORD116-11 (88% identical), SNORD116-12 (87% identical), and 20 more.